HDAC1 (histone deacetylase 1)
Diseases named in the same sentence as HDAC1 in open-access papers (continued):
Sharing a sentence is not in itself a finding about the gene and the disease.
breast cancer (continued). "Apart from a study on HDAC1 and HDAC3 expression in breast cancer describing an overexpression of both isoforms, reports on expression patterns of distinct HDAC isoforms in tumour entities are sparse and most of the cohorts investigated were of a small sample size." (PMID 18212746, 2008). "In normal breast tissues and primary breast cancers HDAC1 expression changes were mostly not significant." (PMID 16638127, 2006). "Similarly, in breast cancer, the overexpression of prostate tumor overexpressed-1 has been found to inhibit DKK1 transcription through the recruitment of histone deacetylase 1(HDAC1) and HDAC2, resulting in decreased levels of histone H3/H4 acetylation at the DKK1 promoter." (PMID 38886806, 2024). "In addition, LSD1 suppresses breast cancer stem cell (CSC) properties by inhibiting epithelial–mesenchymal transition through its interaction with ubiquitously transcribed tetratricopeptide (UTX) and histone deacetylase 1 (HDAC1)." (PMID 38448424, 2024). "Previous studies found the interactions between CHES1 and HDAC1/2 in ERα + breast cancer, so we hypothesized that non-histone CHES1 might undergo acetylation and the acetylation further affected its expression." (PMID 36450706, 2022). "Specifically, NKX2-8 interacts with HDAC1 to form a complex that suppresses PTHrP transcription in breast cancer cells with no bone metastasis, while silencing NKX2-8 could eliminate its inhibition of bone metastasis." (PMID 35707355, 2022). "In non-tumorigenic mammary epithelial cells, HDAC1 is preferentially conjugated to Sumo1 leading to HDAC1 proteolysis, whereas, in breast cancer cells, HDAC1 is predominantly conjugated to Sumo2, promoting HDAC1 protein stability; the specificity for SUMO proteins is dictated by the PIASγ ligase." (PMID 34356679, 2021). "Furthermore, the expression of HDACs (HDAC1 and HDAC2) that interact with the PRC2 complex was also negatively correlated with PTEN expression, consistent with the result of TSA treatment in breast cancer cell lines." (PMID 33750924, 2021). "Additionally, in breast cancer, the transcription factor TWIST recruits an RBBP7/4-MTA2/Mi-2/HDAC1/HDAC2 complex to the proximal regions of the E-cadherin promoter for transcriptional repression via an interaction with RBBP7, which promotes breast cancer cell invasion and metastasis." (PMID 34736517, 2021). "Our results showed that the expression of HDAC1/HDAC2/HDAC3 increased significantly in the tumor tissues compared to the adjacent non‐neoplastic breast tissue, indicating that the three histone deacetylases play vital roles in the initiation and development of breast cancer." (PMID 32686908, 2020). "Notably, HDAC1 and HDAC2 were predominantly located in the nucleus of breast cancer cells." (PMID 32686908, 2020). "Interestingly, increased HDAC1 activity due to its phosphorylation by S6K1 at the downstream of mTORC1 signaling pathway has been shown to inhibit estrogen receptor-alpha expression; thus leading to therapy resistance in breast cancer." (PMID 31637215, 2019). "Furthermore, co-expression of RXR-α and HDAC1 correlated with poor prognosis than either single- or double-negative RXR-α and HDAC1 groups in lung cancer, but not in breast cancer." (PMID 25762635, 2015). "Therefore, quantitative real-time PCR was performed to determine whether HDAC2, HDAC3, and HDAC6 (but not HDAC1) can regulate survivin gene expression in breast cancer cells." (PMID 27065869, 2016). "Activated AR has been shown to cooperate with HDAC1, HDAC2, or HDAC3 to downregulate E-cadherin and promote the migration of non-metastatic breast cancer cells." (PMID 39000339, 2024).
prostate carcinoma (82 papers, 2008 to 2025). A carcinoma that arises from epithelial cells of the prostate gland. "In particular, the overexpression of HDAC1 plays a significant role in the progression of prostate cancer and is linked to a poor prognosis." (PMID 41191566, 2025). "As a central member of HDAC family, HDAC1 has been found to be closely linked to the occurrence and development of prostate cancer." (PMID 41191566, 2025). "HDAC1, -2, and -3 expression was associated with Ki-67-positive prostate cancer cell fractions, and high HDAC2 levels were detected in patients with reduced disease-free survival." (PMID 35582529, 2022). "The SUMO protease SENP1 was identified as a factor that promotes the removal of C-terminal SUMO moieties from human HDAC1 in a prostate cancer model, causing upregulation of the androgen receptor." (PMID 34003109, 2021). "Additionally, CXCL1 reduces fibulin-1 expression in prostate cancer cells and causes the activation of NF-κB, which forms a complex with histone deacetylase 1 (HDAC1)." (PMID 37108425, 2023). "In addition to the role for miR-449 family members in antiviral responses, a previous report has also implicated miR-449a in targeting HDAC1 in prostate cancer cells." (PMID 24086750, 2013). "In prostate cancer cells, apigenin also significantly reduced the expression and activity of HDAC1 and HDAC3, leading to increased H3ac, H4ac." (PMID 41226811, 2025). "PEITC treatment of LNCaP prostate cancer cell line significantly reduced the protein levels of HDAC1, 2, 4, and 6 that correlated with promoter demethylation and activation of a tumor suppressor gene, RASSF1A." (PMID 38596245, 2023). "Apigenin displayed a potent HDAC inhibitor activity in human prostate cancer PC-3 cells, specifically decreasing HDAC1 and HDAC3 activity." (PMID 38004113, 2023). "It is noteworthy that epigenetically targeting HDAC1 is a central step in this model, and therefore, HDAC1 is also an applicable target for prostate cancer chemotherapy." (PMID 36523976, 2022). "Our conclusion is contrary to a previous report that knockdown of HDAC1/2 in the DU145 prostate cancer cell line promotes KLF5 acetylation at K369 but protects KLF5 from degradation." (PMID 35342356, 2022). "For instance, a high expression of class I HDACs including HDAC1 was reported in prostate cancer tissue, and HDAC1 is the most abundant class I HDAC in mammalian cells." (PMID 36523976, 2022). "It has been shown that DNMT1 and HDAC1 levels are higher in prostate cancer than in BPH, implying that they play a role in DNA-methylation-induced chromatin remodeling-induced inactivation of different essential genes." (PMID 36034650, 2022). "The correlated expression of CREPT and HDAC1 was also observed in other cancers including breast, lung, and prostate cancer." (PMID 36230720, 2022). "HDAC1 is overexpressed in many cancers and tumorigenic cell lines and promotes the proliferation of gastric, breast, and prostate cancer cells." (PMID 35565454, 2022). "In particular, HDAC1 is upregulated in hormone refractory prostate cancer, and the overexpression of HDAC1 leads to an increase in prostate cancer cell proliferation." (PMID 33672425, 2021). "Weichert and colleagues demonstrated that HDAC1, HDAC2, and HDAC3 are overexpressed in prostate cancers, whereas increased expression of HDAC1 and HDAC2 correlates with higher Gleason scores." (PMID 33572730, 2021). "In prostate cancer cell lines, re-expression of maspin reportedly increased the expression of tumor suppressor genes that are under the control of HDAC1, such as CK18, p21waf1/CIP1, and Bax30." (PMID 34059749, 2021). "HDAC-5 (as well as HDAC-1, -2, -3 and -4) expression in prostate carcinomas is two-fold higher in pT3 compared to pT2 cases and to connect with tumor recurrence and metastasis." (PMID 33799478, 2021). "Bitter melon MCP30 inhibits histone deacetylase-1 (HDAC-1) activity and promotes histone H3 and H4 acetylation in prostate cancer cells." (PMID 32726914, 2020).
prostate carcinoma (continued). "miR-449a was found to be involved in cell growth and viability regulation through repressing the expression of HDAC-1 in prostate cancer cells." (PMID 33050637, 2020). "In prostate cancer, HDAC1 is targeted by miR-34b (overexpressed, rendering H3Krme3 modification, also targets HDAC4) and miR-449a (downregulated)." (PMID 33050637, 2020). "For example, compound 11b, an indomethacin-SAHA fusion molecule that selectively inhibits COX2 and HDAC6 > HDAC8 > HDAC3 > HDAC2 > HDAC1, inhibits the proliferation of androgen-dependent prostate carcinoma cells." (PMID 31561534, 2019). "Histone deacetylases (HDACs), such as HDAC1, 2, 3 and 4, are highly expressed in prostate cancer tissues and their functions are over-activated." (PMID 31489246, 2019). "It has been reported that HDAC1, 2, and 3 were highly expressed and excessively activated in prostate cancer." (PMID 31271097, 2019). "Later in 2012, Zhipeng Zou published an article and demonstrated that PKD2 and PKD3 coordinated to promote prostate cancer cell invasion through NF-κB and HDAC1-mediated expression and activation of uPA21." (PMID 30718593, 2019). "It was shown that YY1 binds to XAF1 promoter and thereby inhibits its expression in prostate cancer cell lines in a HDAC1 dependent mechanism." (PMID 31824839, 2019). "YY1 inhibits XAF1 expression in prostate cancer cells lines through HDAC1 dependent mechanism and thereby induces cancer progression." (PMID 31824839, 2019). "Kuo’s group reported that CXCL1 activates the NF-κB/HDAC1 pathway in prostate cancer, and that NF-κB can act as an upstream regulator of CXCL144." (PMID 30158589, 2018). "Maspin reintroduction was found to reverse epithelial-to-mesenchymal transition of prostate cancer cells by inhibiting HDAC1 activity and suppressing TGF-β/β-catenin /E-cadherin pathway." (PMID 29029529, 2017). "Complex formation between E2F1 and HDAC1 was detected with immunoprecipitation in bladder and prostate cancer cells." (PMID 25816777, 2015). "DNMT1 and HDAC1 levels are upregulated in prostate cancer, suggesting that they play roles in the inactivation of various critical genes via DNA methylation-induced chromatin remodeling." (PMID 24391925, 2013). "miR-449a targets histone deacetylase-1, inhibiting the expression of histone deacetylase-1, thereby inducing growth arrest of prostate cancer cells." (PMID 23056008, 2012). "In prostate cancer cell lines miR-449a was shown to have growth suppressing activity partly through inhibition of HDAC-1 expression." (PMID 21364938, 2011). "Beside gastric cancer, the expression of miR-449 has also been found to be reduced in several cell lines and in prostate cancer, where it was found to target HDAC1 and induce growth arrest following over-expression in prostate cancer cells." (PMID 21418558, 2011). "Hsa-miR-449a downregulation in adult melanomas is consistent with the downregulation of miR-449a found in prostate cancer tissues and the recent discovery that histone deacetylase 1 (HDAC-1) is a target of miR-499." (PMID 20302635, 2010). "It has previously been shown that miR-449a activates p27 expression by targeted knockdown of HDAC1 in prostate cancer cells." (PMID 20948989, 2010). "The expression level of HDAC1 is positively correlated with the abnormal proliferation of prostate cancer PC3 cells, which could be significantly reversed on treatment with an HDAC inhibitor TSA." (PMID 41191566, 2025). "Targeting HDAC1 has been regarded as a promising approach for the treatment of prostate cancer." (PMID 41191566, 2025). "Studies have shown that miR-449a suppresses HDAC-1 expression, indicating that this microRNA may regulate prostate cancer cell growth and survival through this mechanism." (PMID 40761244, 2025).
prostate carcinoma (continued). "Furthermore, silibinin caused a modest, concentration-dependent increase in overall DNA methyltransferase activity, a decrease in HDAC1 and HDAC2 expression levels, and was associated with EMT and cancer stem cell phenotypes in prostate cancer." (PMID 41226811, 2025). "Notably, HDAC1 and HDAC2 are associated with Gleason grade and recurrence‐free survival (RFS) in prostate cancer." (PMID 41200281, 2025). "PKD3 together with PKD2 initiate prostate cancer cell migration by modulating urokinase-type plasminogen activator (uPA) expression and activation in a nuclear factor kappa B (NF-κB) and histone deacetylase 1 (HDAC1)-mediated manner." (PMID 36672148, 2023). "Increased HDAC1 activity has also been found in prostate cancer." (PMID 37834214, 2023). "HDAC1, being targeted by miR-449a, regulates cell growth and viability in prostate cancer cells." (PMID 35842608, 2022). "In human prostate cancer cell lines and tissues, Maspin interacts with HDAC1." (PMID 36034650, 2022). "A recent study suggested that KLF5 acetylation may regulate KLF5 protein stability and that knockdown of HDAC1/2 in DU145 prostate cancer cells upregulated KLF5 protein acetylation and expression levels by blocking its degradation." (PMID 35342356, 2022). "Interestingly, studies report that HDAC1 has a repressive effect on the levels of androgen in prostate cancer cells, which in turn can be reversed by SENP1 expression." (PMID 33572730, 2021). "Overexpression of HDAC-1, -2 and -3 was reported in most prostate carcinoma cases." (PMID 34441281, 2021). "miR-449a is down-regulated in prostate cancer and its expression negatively correlates with the expression of its direct target, the histone deacetylase 1 (HDAC1); introduction of miR-449a in prostate cancer cells affects cell growth and viability, in part by targeting HDAC1." (PMID 29401683, 2018). "Consistent with a previous finding that class I HDAC members (HDAC1, 2, 3, and 8) are highly expressed in prostate cancers, analysis of TCGA data also showed that expression of these four HDAC genes was upregulated at the mRNA level in tumors compared to normal tissues (Fig EV1A)." (PMID 29523594, 2018). "In addition, HDAC1-shRNA decreased the effect of CXCL1/GROα on migration and invasion, suggesting that HDAC1 is also involved in CXCL1/GROα-mediated prostate cancer progression." (PMID 28624794, 2017). "Furthermore, in prostate cancer, apigenin treatment induced cell cycle arrest and apoptosis, thus significantly inhibiting tumour growth in mice by inhibiting Histone deacetylases (HDACs), especially HDAC1 and HDAC3 expression in prostate cancer cells." (PMID 36557789, 2022). "Moreover, HDAC1 silencing by siRNA results in cell cycle arrest, cell growth inhibition, and induction of apoptosis in breast and colon cancer cells, while HDAC1 overexpression leads to an increase in cell proliferation in prostate cancer cells, indicating that HDAC1 stimulates cancer cell growth." (PMID 28424407, 2017). "In addition, ERG-positive prostate cancers are strongly histone deacetylase 1 (HDAC1)-positive and there is an over-expression of wingless-type MMTV integration site family (WNT)-associated pathways and the simultaneous suppression of tumor necrosis factors and cell death pathways." (PMID 24739220, 2014). "MiR-34b affects HDAC1, HDAC2, and HDAC4 in prostate cancer, while miR-127, miR-411, miR-431, and miR-432 are implicated in HDAC regulation in osteosarcoma." (PMID 40761244, 2025). "Chidamide, in contrast, selectively targets HDAC1, HDAC2, HDAC3, and HDAC10, aligning closely with the four HDAC isoforms most overexpressed in prostate cancer, making it a more biologically relevant candidate for mCRPC treatment." (PMID 41200281, 2025). "Again, studies in other tumor entities revealed an ambiguous picture, with the HDAC1-, HDAC3- and HDAC6-specific inhibitor SN30028 leading to a persistent downregulation of amphiregulin in the prostate carcinoma cell line PC3." (PMID 39864337, 2025).
prostate carcinoma (continued). "In prostate cancer cells, apigenin induced a decrease in HDAC activity, downregulated HDAC1 and 3 expression, and increased acetylation of histones H3 and H4." (PMID 38596245, 2023). "Silibinin also inhibited the expression of HDAC1-2 in DU145 and PC3 human prostate cancer cell lines." (PMID 38004113, 2023). "We analyzed the expression of DNMT1, DNMT3A, DNMT3B, and the class I HDACs HDAC1, HDAC2, HDAC3, and HDAC8 in the PRAD and Taylor data sets and their correlation to HLA-I expression in prostate cancer." (PMID 36050516, 2022). "In human prostate cancer cell lines (DU145 and PC3), silibinin (25–75 μg/mL) decreased the expression levels of HDAC1-2 for 48 h in a concentration-dependent manner." (PMID 35458763, 2022). "HDAC-1 and HDAC-2 were mostly expressed in prostate cancer tissues of patients with Gleason score >7, while HDAC-3 failed to associate with Gleason’s score." (PMID 34441281, 2021). "Together, our results suggest that ARID4B and HDAC1 are likely to function independently to regulate PIK3CA and PIK3R2 in prostate cancer cells." (PMID 31551414, 2019). "Under-expression of these miRNAs has been reported in human prostate cancer tissue, resulting in the repression of HDAC-1 (histone deacetylase 1)." (PMID 26934316, 2016). "In prostate cancer, TCF21 interacts with AR and inhibits its transactivation through the recruitment of HDAC1." (PMID 27028856, 2016). "Expression levels of PTEN, HDAC1 and SFPQ hub proteins in Prostate Cancer (Cancer) and adjacent benign tissues (Benign)." (PMID 23737958, 2013). "In human prostate cancer PC-3 cells, apigenin (20–40 μM) acts as a potent HDAC inhibitor, which induces noticeable suppression of the HDAC protein activity (41% and 62%), especially HDAC1 and HDAC3." (PMID 35458763, 2022). "In the balanced differentiated group of young and old prostate cancer patients, MYC and HDAC1 genes were emerged as a central node and uniquely upregulated in young men whereas VEGFA is the key node in old men and found to be down regulated along with HLA and ANXA2 genes in old patients." (PMID 33575208, 2020). "In addition, while knockdown of ARID4B decreased expression of p110α and p85β in the prostate cancer cell lines PC3, DU145, and LNCaP, knockdown of HDAC1 increased expression of p110α and p85β." (PMID 31551414, 2019). "Previously, we developed novel amide-bearing hydroxamic acid derivatives as class-selective HDAC inhibitors termed SL142 and SL325 and reported that these small molecules show more significant HDAC1, HDAC4 and HDAC6 inhibitory activity in human prostate cancer cells LNCaP than SAHA." (PMID 21079797, 2010). "HDAC1 could induce the activation of urokinase-type plasminogen activator (uPA), matrix metalloprotease-1 (MMP-1) and MMP-2, but suppressed E-cadherin in order to accelerate the invasion and migration of prostate cancer cells." (PMID 38800374, 2024). "In glioblastoma and prostate cancer cells, TSA and SAHA but not MS275 targeted HDAC1 and 6, thereby disrupting the HDAC and protein phosphatase 1 complex." (PMID 23951179, 2013). "Here we show that fimepinostat, a dual HDAC1/2 and PI3K/AKT inhibitor investigated clinically in other cancer types but not prostate cancer, may overcome this heterogeneity by effectively inhibiting both ARPC and NEPC subtypes of CRPC." (PMID 37823778, 2023).